TDRKH (tudor and KH domain containing)
Description:
Participates in the primary piRNA biogenesis pathway and is required during spermatogenesis to repress transposable elements and prevent their mobilization, which is essential for the germline integrity. The piRNA metabolic process mediates the repression of transposable elements during meiosis by forming complexes composed of piRNAs and Piwi proteins and govern the methylation and subsequent repression of transposons. Required for the final steps of primary piRNA biogenesis by participating in the processing of 31-37 nt intermediates into mature piRNAs. May act in pi-bodies and piP-bodies by transferring piRNA precursors or intermediates to or between these granules.
Synonyms: TDRD2
Tractability: PROTAC: UniProt records ubiquitination sites on it; ubiquitination databases record sites on it; its protein half-life has been measured.
Gene: Protein-coding gene on chromosome 1 (151,769,799 to 151,791,416, reverse strand). Ensembl gene ENSG00000182134.
Subcellular location: Cytoplasm; Mitochondrion
Subcellular location (Human Protein Atlas): Cytosol; Centrosome
Pathways (Reactome):
Gene expression (Transcription): PIWI-interacting RNA (piRNA) biogenesis
Gene Ontology:
Molecular function: protein binding; nucleic acid binding; RNA binding
Biological process: fertilization; male meiotic nuclear division; P granule organization; piRNA processing; spermatogenesis
Cellular component: mitochondrion; cytoplasm; P granule; pi-body; piP-body
Genetic constraint (gnomAD): Loss-of-function variants: 28 observed, 63.86 expected, observed/expected ratio (o/e) 0.44, 90% interval 0.32 to 0.6. The upper end of that interval is the gene's LOEUF score, 0.6, which puts it in group 2 of 6, group 1 being the genes least tolerant of losing a copy. Missense variants: 540 observed, 721.39 expected, observed/expected ratio (o/e) 0.75, 90% interval 0.7 to 0.8. Synonymous variants: 219 observed, 259.3 expected, observed/expected ratio (o/e) 0.84, 90% interval 0.76 to 0.94.
Homologues: Orthologues: macaque TDRKH (99% identical), chimpanzee TDRKH (97% identical), rat Tdrkh (92% identical), dog TDRKH (92% identical), mouse Tdrkh (91% identical), guinea pig TDRKH (90% identical), pig TDRKH (87% identical), tropical clawed frog tdrkh (39% identical). Paralogues in human: TDRD15 (18% identical), TDRD6 (18% identical), TDRD1 (15% identical), TDRD5 (14% identical), TDRD7 (14% identical), TDRD10 (9% identical).
Diseases named in the same sentence as TDRKH in open-access papers:
TDRKH is named in the same sentence as 11 diseases in open-access papers, as found by Europe PMC text mining. Sharing a sentence is not in itself a finding about the gene and the disease. The quoted sentences say what the papers report.
asthma (1 paper, 2020). "Additionally, the identified childhood-onset asthma-associated gene of JAZF1 has evidence of genetic interactions with identified genes of AHI1, NSMCE1, TDRKH, CD52, and HLA-DRB1 based on a genome-wide map of genetic interaction inferred from radiation hybrid genotypes." (PMID 32867763, 2020).
autoimmune disease (1 paper, 2025). A disorder resulting from loss of function or tissue destruction of an organ or multiple organs, arising from humoral or cellular immune responses of the individual to their own tissue constituents. "Despite our study suggesting a potential causal relationship between TDRKH and PsO, there is currently no research linking TDRKH to autoimmune diseases." (PMID 40564099, 2025).
psoriasis (1 paper, 2025). An autoimmune condition characterized by red, well-delineated plaques with silvery scales that are usually on the extensor surfaces and scalp. "Meanwhile, LTA, TDRKH, and DDR1 were expressed exclusively in T cells from psoriasis biopsy samples, while HLA-E and ICAM3 exhibited psoriasis-specific- expression." (PMID 40564099, 2025).
tumor (1 paper, 2021). "SCAMP3 level was positively correlated with disease stages and tumor grades and negatively correlated with patient survival; SOX4, STK39, TARBP1, and TDRKH can be regarded as potential prognosticators and therapeutic targets for HCC." (PMID 34277395, 2021).
TDRKH also shares sentences with these, for which no sentence is quoted: adult onset asthma (1 paper); allergic disease (1); breast carcinoma (1); glioma (1); liver cancer (1); lymph node metastasis (1); Onset (1).